KLRK1 (killer cell lectin like receptor K1)
Diseases named in the same sentence as KLRK1 in open-access papers (continued):
Sharing a sentence is not in itself a finding about the gene and the disease.
tumor (continued). "KLRK1 (or NKG2D) is also an activating receptor expressed by NK cells and T cell subsets, can augment the cytotoxicity of NK cells/T cells or synergize with immune checkpoint inhibitors to eliminate tumor cells." (PMID 33549054, 2021). "In contrast to TCGA LGG dataset, high tumor expression of KLRC1 and KLRC2 in CGGA LGG patients were associated with improved prognosis, but not KLRC3, KLRC4 or KLRK1." (PMID 34539622, 2021). "KLRK1 recognizes a range of ligands upregulated by transformed cells, such as MHC class I chain-related sequence (MIC) A and MICB, which are major determinants of NK cell tumor cytolysis in humans." (PMID 34539622, 2021). "RAE-1 was highly expressed on tumors developing in both wild-type and Klrk1−/− mice indicating that tumor progression was not the consequence of escape via ligand editing." (PMID 30150983, 2018). "Tumor NK cells downregulated canonical NK activation markers, such as FASLG, TNFSF10, KLRK1, GZMB, and KLRD1, the latter having both inhibitory and activator capabilities but being a marker of favorable prognosis in human cancers if present in either the serum or tumor." (PMID 41208961, 2025). "High tumor expression of TNFRSF14 and CD160, but not TNFSF14, LTA, or BTLA, was associated with improved BLCA patient prognosis, suggesting that the TNFRSF14–CD160 interaction, like KLRK1, is a prominent pathway of NK cell tumor surveillance in BLCA." (PMID 34858395, 2021). "Therefore, caution should be exercised in fully characterizing the tumor (e.g., CD4 or CD8; does the tumor itself bear KLRK1, or is it expressed by the infiltrating T cells) to ascertain whether KLRK1 both as a biomarker and a potential treatment target is beneficial or detrimental." (PMID 38026637, 2023). "In line with our hypothesis proposing that NKG2D ligand expression is maintained rather than immunoedited in this type of tumour, we observed that RAE-1 was similarly expressed in both Klrk1+/+ and Klrk1−/− mice." (PMID 28128200, 2017).
cancer (477 papers, 2008 to 2026). A tumor composed of atypical neoplastic, often pleomorphic cells that invade other tissues. "One of the earliest studies describing KLRK1 polymorphisms was based on previous indications of the relationship between natural cytotoxic activity of peripheral blood lymphocytes and cancer susceptibility in the Saitama population." (PMID 34200375, 2021). "Moreover, blockade drugs for EGFR and PD-1 can enhance the effective of NKG2D, encoded by KLRK1, lead to cancer cell recognition and killing by NK effector cells." (PMID 35132098, 2022). "Killer cell lectin-like receptor K1 (KLRK1), a marker highly expressed in immune cells, can bind to its ligands expressed by cancer cells to exert its antitumor effect." (PMID 37565867, 2023). "Killer cell lectin-like receptor K1 (KLRK1), a marker highly expressed in immune cells, can bind to ligands expressed on cancer cells to exert its antitumor effect." (PMID 37565867, 2023). "KLRK1 can result in the activation of NK and T cells, which have been chosen as a therapeutic target for the treatment of immune diseases and cancers." (PMID 36675674, 2022). "NK cells effectively inhibit the function of cancer cells through activation of killer cell lectin like receptor K1 (KLRK1) and natural cytotoxicity triggering receptors 1 and 2 (NCR1 and NCR2)." (PMID 33276627, 2020). "At the same time, potentiated NK-cell mediated killing was enhanced by increased binding of the NK cell activating receptor NKG2D (KLRK1 gene) to its ligands present on the cancer cells." (PMID 32937961, 2020). "The function of NKG2D itself can also differ with different NKG2D (KLRK1) gene polymorphisms and associate with susceptibility to cancer." (PMID 30150983, 2018). "Carcinoma was the most represented lesion in both cohorts, with similar incidence in Klrk1+/+and Klrk1−/−mice (73.3% versus 70.6% respectively)." (PMID 28128200, 2017). "Recently, the role of KLRK1 in cancer immunosurveillance and immune escape is widely studied." (PMID 35132098, 2022). "KLRK1 decreased the migration distance of cancer cell (P < 0.05)." (PMID 35132098, 2022). "For instance, the rs1049174 polymorphism in the KLRK1 gene, which encodes NKG2D, has been linked to reduced receptor expression and impaired cytotoxicity, thereby increasing susceptibility to HPV-related cancers and influencing outcomes in hematological malignancies." (PMID 40862731, 2025). "Meanwhile, the highly expression of HLA-E as a ligand for KLRC1, KLRK1, and NKG2A/CD94 on the surface of NK cells can help cancer cells evade immune killing by NK cells." (PMID 39583114, 2024). "In most cancers, CD86, TNFSF14, KLRK1, CD48, CD40LG, CD28, C10orf54, ENTPD1, CXCL12, and POLD2 are negatively correlated (p < 0.05)." (PMID 36081989, 2022). "Firstly, this study only investigated the role of KLRK1 and ULBP1-3 inHNSCC, and other types of cancers may have different immune escape mechanisms." (PMID 37565867, 2023). "Similarly, ULBP1 binds to its cognate receptor NKG2D (KLRK1) on effector lymphocytes, enhancing the cytolytic activity of cytotoxic killer cells towards carcinoma target cells." (PMID 35572601, 2022).
infection (113 papers, 2007 to 2025). The state of being infected such as from the introduction of a foreign agent such as serum, vaccine, antigenic substance or organism. "The KLRK1 module was related to 36 biological processes and 3 diseases, targeting susceptibility to natural killer cell-mediated cytotoxicity, leukocyte mediated immunity and innate immune response and diseases involving infection." (PMID 38530405, 2024). "This was most pronounced for KLRK1, where at 24 hours after infection, more than 60% of L.8 cells in resisters expressed the gene versus only 20% in LTBI cells (a 3-fold difference)." (PMID 39836471, 2025). "Wild type Ly49H+ NK cells proliferate faster than their Klrk1−/− counterparts following infection with a virus that drives overexpression of the NKG2D ligand Rae1γ." (PMID 29568297, 2018). "Of the activating receptors, NKG2D (Klrk1) is distinguished as it is present on virtually all NK cells, targets stress- and infection-induced ligands, and can overcome inhibitory signals to mediate cytotoxicity and cytokine release." (PMID 24130907, 2013).
immune diseases (5 papers, 2010 to 2022). "NKG2D (KLRK1), for instance, is a natural killer cell receptor which has an extensively published connection with the innate immune response system's ability to detect stress and senescent cells, and thus, along with its ligands, is considered a therapeutic target for immune diseases." (PMID 28879183, 2017).
KLRK1 also shares sentences with these, for which no sentence is quoted: multiple myeloma (60 papers); leukemia (54); hepatocellular carcinoma (52); glioma (48); ovarian carcinoma (41); acute myeloid leukemia (38); pancreatic cancer (36); glioblastoma (35); neuroblastoma (30); rheumatoid arthritis (28); gastric cancer (27); osteosarcoma (27); Autoimmunity (25); liver fibrosis (23); hematological malignancies (20); Crohn disease (18); systemic lupus erythematosus (16); alopecia areata (15); colon carcinoma (15); celiac disease (14); liver cancer (12); type 1 diabetes (12); acute lymphoblastic leukemia (11); mesothelioma (11); HIV-1 infection (10); influenza (10); myelodysplastic syndrome (10); colitis (9); metastatic colorectal cancer (9); Obesity (9).
A further 203 diseases each share a sentence with KLRK1 in 9 papers or fewer.